EGFR (epidermal growth factor receptor)
Diseases named in the same sentence as EGFR in open-access papers (continued):
Sharing a sentence is not in itself a finding about the gene and the disease.
lung adenocarcinoma (continued). "While the EGFR mutation status can be used to predict the response of advanced-stage lung adenocarcinoma to EGFR-TKIs, the accuracy of this prediction was not satisfying." (PMID 38786296, 2024). "It has been previously reported that prostaglandin E2 (PGE2), one of the main mediators of inflammation, can activate Src kinases through EP3 receptors, which in turn transactivate EGFR (regardless of the presence of a ligand) in lung adenocarcinoma cells." (PMID 38145300, 2024). "With this background it appears unsurprising that in LTS patients, targetable alterations are much more frequent than among non-selected patients with adenocarcinoma of the lung (EGFR: 41 vs. 11%; ALK: 8 vs. 4.8%)." (PMID 37646818, 2024). "Although EGFR-TKI treatment has been shown to be effective in most patients with EGFR mutant lung adenocarcinomas, no response is observed in 5%–25% of patients due to intrinsic resistance to these drugs." (PMID 38953007, 2024). "According to their results, HPV16E6/18E6 and EGFR expression in NSCLC correlates with a greater survival rate in older lung adenocarcinoma patients without brain metastasis, with a smoking history, and with wild-type EGFR status." (PMID 38255725, 2024). "Rearrangement of the ROS1 gene is observed in ~1–2% of patients NSCLC, particularly in non-smokers, those with lung adenocarcinomas, and patients without alterations in the EGFR or ALK genes." (PMID 38499647, 2024). "For further in vivo evidence, and given the important roles of EGFR/MAPK/ERK/CREB in lung adenocarcinoma, we evaluated the Cancer Genome Atlas (TCGA) lung adenocarcinoma RNA-seq results, comparing MAPK/ERK activating KRASG12X mutant (X is A, C, D, S, or V) with non-variant samples." (PMID 39138174, 2024). "Improving immunotherapy efficacy for EGFR‐negative lung adenocarcinoma (LUAD) patients remains a critical challenge, and the therapeutic effect of immunotherapy is largely determined by the tumor microenvironment (TME)." (PMID 38886907, 2024). "For example, in an EGFR L858R lung adenocarcinoma patient (patient #1), erlotinib was not effective." (PMID 39138315, 2024). "Patients with lung adenocarcinoma who have never smoked (NSLA) and lack key driver mutations, such as those in the EGFR and ALK genes, face limited options for targeted therapies." (PMID 39300154, 2024). "The first-line EGFR inhibitor gefitinib and HE4 shRNA had no synergistic inhibitory effect on the growth of lung adenocarcinoma cells, while the third-line EGFR inhibitor osimertinib showed additive anti-proliferative effects." (PMID 38827327, 2024). "One patient (case NCCLu-027) was a never-smoking 84-year-old woman with stage IV lung adenocarcinoma lacking driver oncogenes such as EGFR." (PMID 38398169, 2024). "Although targeted therapies such as epidermal growth factor receptor (EGFR) inhibitors have exhibited efficacy against lung adenocarcinoma, there are no first-line targeted therapies available for LUSC2." (PMID 38495491, 2024). "HER2 amplifications, on the other hand, have also been described as a potential mechanism of acquired resistance to EGFR TKI, as FISH analysis has revealed that HER2 was amplified in 12% of tumours with acquired resistance, versus only 1% of untreated lung adenocarcinomas." (PMID 39421181, 2024). "The prognostic value of SII in patients with EGFR mutant lung adenocarcinoma receiving thoracic radiotherapy is not clear." (PMID 36070068, 2023). "EGFR and ERBB2/Her2 are well-known oncogenic genes in human lung adenocarcinoma." (PMID 37513116, 2023). "Significantly more patients were in pretreatment KPS > 70, had lung adenocarcinoma, had the ALK/EGFR mutation, were not synchronous, had extracranial metastases, were supratentorial or multiple, and had no radiotherapy." (PMID 36826133, 2023). "Thus the mechanism regarding the role of EGFR and MMP11 in regulating immunity in lung adenocarcinoma is worthy of further exploration." (PMID 36756152, 2023).
lung adenocarcinoma (continued). "For lung adenocarcinoma with just EGFR L858R mutation, the Observation group had a better ORR, mPFS, and 2-year survival than the EGFR-TKIs alone group, but DCR and 1-year survival were not significantly different." (PMID 37390279, 2023). "Our findings are in agreement with the previous report of C1orf74 in lung adenocarcinoma, which is not hormonally regulated like cervical cancer, but showed a correlation of C1orf74 with the regulation of the EGFR/AKT/mTORC1 pathway." (PMID 37947608, 2023). "In conclusion, our results indicate the role of DCLK1 in the development of EGFR-TKI resistance in lung adenocarcinoma that has undergone EMT, and targeting DCLK1 could be used as a new option for posterior-line treatment of EGFR-TKI-acquired resistance tumor." (PMID 37239162, 2023). "Common examples are HER2 in breast and gastric cancers, EGFR in lung, colorectal, and head and neck cancers, KRAS in colorectal, pancreatic, and lung adenocarcinoma, BRAF in melanoma and colorectal cancer, ALK in some NSCLC cases, and PSA as a prostate cancer biomarker." (PMID 38202898, 2023). "The most frequent alterations among Asians are epidermal growth factor receptor (EGFR) mutations, which have been detected in up to 60-70% of lung adenocarcinomas in Asian never-smokers, in contrast to 10-15% of Caucasian patients." (PMID 37581146, 2023). "Secondly, since the purpose of this article is to clinically retrospectively evaluate the effect of ZLJT combined with EGFR-TKI in delaying drug resistance in advanced lung adenocarcinoma, there is a lack of experimental verification of pathway research." (PMID 37990309, 2023). "Despite the proportion of tumors harboring EGFR, ALK, or KRAS alterations being consistent with the frequency reported in lung adenocarcinoma, the reduced subgroup size, especially for ALK-positive cases, might have limited the strength of the models." (PMID 37760521, 2023). "The tyrosine kinase inhibitors (TKIs) of EGFR and ALK have been proven remarkably beneficial in bringing a better clinical outcome in patients with lung adenocarcinoma in both adjuvant or salvage settings, whose impact upon the observation of PORT efficacy was not considered by these RCTs." (PMID 37188197, 2023). "To further study the impact of neutrophil to lymphocyte and platelet to lymphocyte ratios on the prognosis of patients with stage I EGFR-altered lung adenocarcinoma, we established nomograms with and without these peripheral blood markers." (PMID 37941434, 2023). "In some series, the cancer type was not a significant variable, while in others, renal and lung adenocarcinoma histology have been identified as risk factors; in particular, ALK+ and EGFR+ lesions were associated with higher rates." (PMID 37046755, 2023). "Of the 11 patients with lung adenocarcinoma (LUAD), 6 (54.6%) had at least one actionable mutation, of which 3 (27.3%) were with EGFR mutations, 3 (27.3%) showed KRAS mutations, and none were with BRAF mutations." (PMID 37769655, 2023). "YAP1 was a poor prognostic factor of EGFR-mutant NSCLC population rather than lung adenocarcinoma (LUAD) patients." (PMID 37388902, 2023). "In the case of lung adenocarcinomas (ADC) development in never-smokers from PM2.5 exposure from air pollution, tumor promotion appears to be a key mechanism acting on lung cells with EGFR driver-mutations acquired naturally through ageing." (PMID 37696458, 2023). "Interestingly, a recent study has demonstrated that a relationship between EGFR and MCM4 is observed in lung adenocarcinoma." (PMID 37737200, 2023).
lung adenocarcinoma (continued). "This is critical to EGFR-driven lung adenocarcinoma as it commonly occurs in individuals who have never smoked and do not qualify for current screening protocols." (PMID 38260835, 2023). "Finally, the TCGA lung adenocarcinoma (LUAD) database was consulted to study the expression of ACE2 in EGFR- and KRAS-mutant samples and ACE2 expression was correlated with EGFR/HER, RAS, BRAF, ROS1, ALK, and MET mRNA expression." (PMID 36077610, 2022). "This was significantly higher than that observed in lung adenocarcinomas with an EGFR mutation, with a KRAS mutation but lacking an ALK mutation, or with either an EGFR or KRAS mutation (all P < .005)." (PMID 35984185, 2022). "It was reported that ROR1 repression inhibits the growth of lung adenocarcinoma regardless of EGFR status, and leads to multiple acquired resistance mechanisms, including EGFR T790M, MET amplification and hepatocyte growth factor (HGF) overexpression." (PMID 36497465, 2022). "ALK, EGFR, and TTF1 are commonly used to detect lung adenocarcinoma." (PMID 35546675, 2022). "We also found that SD affected various signaling pathways to play a pharmacological role against the growth of lung adenocarcinoma cells, including ERBB2 signaling pathway, epidermal growth factor receptor signaling pathway, and phosphatidylinositol-mediated signaling." (PMID 35190747, 2022). "Compared with ALK, EGFR, and TTF1, UCHL1 has higher predictive accuracy for lung adenocarcinoma." (PMID 35546675, 2022). "Previous studies have identified several clinical features related to the prevalence of EGFR mutations in NSCLC such as female sex, Asian ethnicity, lung adenocarcinoma, and never-smoking status." (PMID 36341427, 2022). "In summary, this single-institutional, retrospective study showed that in patients with lung adenocarcinoma and BM, upfront BRT was associated with a significantly longer intracranial PFS, especially in patients without EGFR (19 or 21) mutation." (PMID 35069906, 2022). "In more details, the GAS5 SNP rs145204276 Ins/Del + Del/Del causes a higher tumor stage and leads to distal metastases in non-smokers with lung adenocarcinoma and wild-type EGFR." (PMID 36011604, 2022). "Specifically, the clinical significance of E6+tEGFR+ expression was identified in lung adenocarcinoma patients with older age, no brain metastasis, smoking history, and wild-type EGFR status." (PMID 36358752, 2022). "Blocking zDHHC20-mediated EGFR S-acylation has also been shown to reduce PI3K signaling and MYC levels and suppress cell growth in vitro and tumor growth in an in vivo model of KRAS-mutant lung adenocarcinoma." (PMID 36087837, 2022). "Moreover, an NSCLC tissue array consisting of 30 human lung adenocarcinoma samples was evaluated by IHC staining, demonstrating that NK1R protein level was positively related to EGFR expression." (PMID 35013118, 2022). "The emergence of targeted therapy of epidermal growth factor receptor (EGFR) tyrosine kinase inhibitor (TKI) paradigms has radically changed advanced NSCLC treatment and improved patient survival rates, especially for advanced lung adenocarcinoma." (PMID 36276079, 2022). "The authors described a histological transformation of EGFR-mutant lung adenocarcinoma in a middle-aged never smoker woman treated with TKI." (PMID 35456982, 2022). "For example, the chemotherapy agent doxorubicin, in combination with Se, markedly decreased the proliferation, migration, and invasion, and increased the apoptosis of the EGFR and KRAS-activating mutant A549 lung adenocarcinoma cells as compared to doxorubicin alone." (PMID 36547898, 2022).
lung adenocarcinoma (continued). "For example, the pathways reported potentially to mediate CD109′s tumorigenic effect in lung adenocarcinoma include JAK-SAT, Hippo-YAP, and EGFR-AKT-mTOR, but their relative significance and potential cross-talk in mediating CD109 action in lung adenocarcinoma are poorly understood." (PMID 35954339, 2022). "EGFR is a major oncogenic driver in NSCLC and can often be muted in lung adenocarcinoma." (PMID 35454856, 2022). "The results confirm that ANGPTL4 promotes the development of resistance to EGFR-TKIs in lung adenocarcinoma cells and that ANGPTL4 may be a potential target for overcoming resistance to EGFR-TKIs." (PMID 36467503, 2022). "Although EGFR gene status is not routinely examined in surgically resected specimens, it is worthwhile to examine any EGFR gene mutations in the specimens because EGFR-TKIs may extend survival in patients with postoperative recurrence of EGFR-mutated lung adenocarcinoma." (PMID 34652430, 2022). "A previous study reported the co-expression of ADAM15 and αVβ3 in lung adenocarcinoma, therefore, we examined whether integrin signalling is involved in the ADAM15-induced EGFR signalling pathway." (PMID 35597804, 2022). "Patient No. 17, a 75-year-old female, never smoker, was diagnosed with right lung adenocarcinoma positive for EGFR ex19del." (PMID 33718183, 2021). "In summary, our study demonstrated that denosumab had no prognostic effects in patients with lung adenocarcinoma and BM who were treated with first-line EGFR-TKIs." (PMID 34577890, 2021). "Furthermore, the continuous activation of EGFR leads to an increase in Sox2 expression, resulting in the maintenance of LCSC features in EGFRm lung adenocarcinoma." (PMID 34771484, 2021). "A 73-year-old male patient was diagnosed with left lung adenocarcinoma IVa, EGFR, ALK, ROS1 negative." (PMID 34521373, 2021). "Although activated c-Src did not enhance EGFR-related survival pathways in lung adenocarcinoma, the possibility of c-Src inactivation resulting in caspase-8 dephosphorylation to facilitate cell death was considered." (PMID 34367939, 2021). "Epidermal growth factor receptor (EGFR)-mutant lung adenocarcinoma occurs predominantly in never smokers or oligosmokers and exhibits a relatively low TMB." (PMID 34391887, 2021). "To address this, we aimed to assess OS after primary tumor resection versus no resection in lung adenocarcinoma patients with occult pleural dissemination treated with EGFR-TKIs." (PMID 33954108, 2021). "Our team harvested 33 pairs of EGFR-mutant lung adenocarcinoma and noncancerous tissues, of which 13 pairs were accessible to patient-derived xenografts (PDXs) or tumors." (PMID 34367939, 2021). "A 66-year-old woman (patient 29) was diagnosed with stage Ia lung adenocarcinoma at disease baseline and underwent a radical right upper lobectomy with video-assisted thoracoscopic surgery (VATS) in February 2010, EGFR 19del was discovered in the primary lung lesion by ARMS-PCR." (PMID 33828979, 2021). "In our subsequent in vitro study, we further explored combined gefitinib with bevacizumab significantly ameliorated MAPF-induced endothelial angiogenesis independent of EGFR status of lung adenocarcinoma patients." (PMID 34680445, 2021). "The knockdown of Her-2, Her-3, or Her-4 was incapable of affecting EGFR-related signaling as EGFR knockdown in the EGFR-nonaddictive lung adenocarcinoma cells." (PMID 34367939, 2021). "To identify the changes in mitogenic signalling pathways that inhibit tumour growth in the mouse model, we transiently knocked down DHHC20 in an oncogenic Kras-harbouring lung adenocarcinoma cell line NCI-H23 and examined the differences in signalling downstream of EGFR." (PMID 34610265, 2021). "In the present study, we found that the frequency of WWOX SNPs rs11545028, rs12918952, rs3764340, rs73569323, and rs383362 was not significantly different between wild-type and mutant EGFR lung adenocarcinoma patients." (PMID 34948746, 2021).
lung adenocarcinoma (continued). "Previous studies have shown that SCC patients with EGFR mutations conferred responsiveness to EGFR-TKIs, with a non-inferior ORR (25–49%) to that of lung adenocarcinoma patients." (PMID 34195081, 2021). "We report a 71 year-old male patient diagnosed with advanced lung adenocarcinoma lacking key driving genes (EGFR, ALK, and ROS-1), and low expression of PD-L1 on tumor cells (10-15%)." (PMID 34993345, 2021). "A 73-year-old male patient was diagnosed with left lung adenocarcinoma T3N3M1b stage IVa, EGFR, ALK, ROS1 negative, PDL1 1–49%." (PMID 34521373, 2021). "EGFR, ALK, and KRAS were common driver gene in Chinese patients with stage IV lung adenocarcinoma." (PMID 33997043, 2021). "We launched a multi-center retrospective study to evaluate the efficacy and toxicity of adjuvant TKIs with or without chemotherapy in epidermal growth factor receptor (EGFR)-mutant stage III-pN2 lung adenocarcinoma." (PMID 33916930, 2021). "Most patients were females (59%), with EGFR mutant stage III–IV lung adenocarcinoma (90.5%) and without smoking history (62%)." (PMID 33520716, 2020). "Case Presentation: A 61-year-old female (never smoker) who initially presented with headache and dizziness was diagnosed with lung adenocarcinoma with multiple brain metastasis (cT2aN3M1b stage IV), and was negative for EGFR and ALK." (PMID 32351894, 2020). "Patient 3: The third case study is a 59-year-old female with a diagnosis of EGFR-negative lung adenocarcinoma." (PMID 31935818, 2020). "Epidermal growth factor receptor (EGFR) is known to be overexpressed on the cell surface of various types of malignant tumors, including breast and lung adenocarcinomas (40% of cases), anal cancers, glioblastoma (50%) and epithelial tumors of the head and neck (80–100%)." (PMID 31906300, 2020). "Epidermal growth factor receptor wild-type, anaplastic lymphoma kinase-negative primary lung adenocarcinoma with an asymptomatic solitary BM (cTxNxM1b, IVA)." (PMID 32899099, 2020). "During the study period, sputum derived from patients with lung adenocarcinoma contained carcinoma cells in some cases, but all cases were EGFR-negative based on histological diagnosis." (PMID 32033355, 2020). "The tumor T-status, rate of distant metastasis and the distribution of cell differentiation of lung adenocarcinoma did not alter in different EGFR presentation with CA9 SNP rs2071676 (all p > 0.05)." (PMID 32365566, 2020). "Subjects with EGFR positive lung adenocarcinoma showed higher rates of female sex, never smokers, and TNM stage IV." (PMID 32053675, 2020). "Here, we report a rare case in which a patient with a lung adenocarcinoma harboring an insertion in EGFR exon 20 did not respond to osimertinib." (PMID 33080698, 2020). "Pemetrexed/carboplatin plus anlotinib could be considered for patients with EGFR wild-type, ALK-negative lung adenocarcinoma, and BM." (PMID 32899099, 2020). "Epidermal growth factor receptor (EGFR) wild-type advanced primary lung adenocarcinoma without brain or bone metastasis." (PMID 33031343, 2020). "In conclusion, we showed that ERβ1 localized in the cell cytoplasm by interacting with ERβ5, inducing non-genomic signaling activation, and promoting EGFR TKI treatment resistance in EGFR-mutant lung adenocarcinoma." (PMID 33585221, 2020).